UGT2A2 (UDP glucuronosyltransferase family 2 member A2)
Description:
UDP-glucuronosyltransferase (UGT) that catalyzes phase II biotransformation reactions in which lipophilic substrates are conjugated with glucuronic acid to increase the metabolite's water solubility, thereby facilitating excretion into either the urine or bile. Essential for the elimination and detoxification of drugs, xenobiotics and endogenous compounds. Catalyzes the glucuronidation of endogenous estrogen hormone estradiol. Contributes to bile acid (BA) detoxification by catalyzing the glucuronidation of BA substrates, which are natural detergents for dietary lipids absorption. Shows a potential role in detoxification of toxic waste compounds in the amniotic fluid before birth, and air-born chemical after birth.
Synonyms: UDPGT 2A2
Tractability: Antibody: UniProt predicts a signal peptide or a membrane-spanning region.
Safety:
Unwanted effects reported when the protein is acted on. In parentheses: how it was acted on, where the effect was seen, and who reports it.
drug toxicity (source: ClinPGx)
Gene: Protein-coding gene on chromosome 4 (69,588,417 to 69,639,642, reverse strand). Ensembl gene ENSG00000271271.
Subcellular location: Endoplasmic reticulum membrane
Pathways (Reactome):
Drug ADME: Aspirin ADME
Metabolism: Glucuronidation
Gene Ontology:
Molecular function: glucuronosyltransferase activity; UDP-glycosyltransferase activity
Biological process: bile acid metabolic process; response to symbiont; xenobiotic metabolic process
Cellular component: endoplasmic reticulum membrane
Genetic constraint (gnomAD): Loss-of-function variants: 60 observed, 52.21 expected, observed/expected ratio (o/e) 1.15, 90% interval 0.93 to 1.42. The upper end of that interval is the gene's LOEUF score, 1.42, which puts it in group 5 of 6, group 1 being the genes least tolerant of losing a copy. Missense variants: 762 observed, 658.89 expected, observed/expected ratio (o/e) 1.16, 90% interval 1.09 to 1.23. Synonymous variants: 242 observed, 222.57 expected, observed/expected ratio (o/e) 1.09, 90% interval 0.98 to 1.21.
Homologues: Orthologues: rat Ugt2a1 (84% identical), mouse Ugt2a2 (84% identical), zebrafish ugt2a7 (53% identical), zebrafish ugt2b1 (52% identical), zebrafish ugt2b5 (52% identical), zebrafish ugt5a2 (40% identical), zebrafish ugt5a1 (40% identical), zebrafish ugt5b4 (40% identical), zebrafish ugt5b2 (38% identical), zebrafish ugt5c1 (38% identical), zebrafish ugt5c3 (38% identical), zebrafish ugt5g1 (38% identical), and 94 more. Paralogues in human: UGT2A1 (70% identical), UGT2A3 (62% identical), UGT2B17 (62% identical), UGT2B4 (62% identical), UGT2B15 (61% identical), UGT2B7 (60% identical), UGT2B10 (58% identical), UGT2B11 (58% identical), UGT2B28 (57% identical), UGT1A1 (43% identical), UGT1A3 (42% identical), UGT1A5 (42% identical), and 9 more.
Diseases named in the same sentence as UGT2A2 in open-access papers:
UGT2A2 is named in the same sentence as 4 diseases in open-access papers, as found by Europe PMC text mining. Sharing a sentence is not in itself a finding about the gene and the disease. The quoted sentences say what the papers report.
COVID-19 (5 papers, 2022 to 2024). A disease caused by infection with severe acute respiratory syndrome coronavirus 2. "Previous studies, including genome-wide association studies (GWAS), have identified genetic variants near the UGT2A1 and UGT2A2 genes that are linked to anosmia in COVID-19 patients." (PMID 39767184, 2024). "Interestingly, UGT2A1 and UGT2A2 have recently been implicated in COVID-19-associated loss of smell and taste." (PMID 38098019, 2023). "A genome-wide association study (GWAS) of COVID-19-related loss of smell and taste of self-reported participants revealed a significant locus in the vicinity of the UGT2A1 and UGT2A2 genes." (PMID 36835589, 2023). "While the specific function of UGT2A1/UGT2A2 is not clear in COVID-19-related loss of smell, this study provides a first genetic link between the physiology of infected cells and subsequent functional olfactory impairment." (PMID 36835589, 2023).
Anosmia (4 papers, 2024). An inability to perceive odors. "Both UGT2A1 and UGT2A2 are enriched in the olfactory epithelium and govern odorant metabolism, and it is of interest for future study to delineate the mechanisms underlying their contributions to anosmia and ageusia." (PMID 38846354, 2024). "Besides, a multi-ancestry GWAS has identified a correlation between the UDP glucuronosyltransferase family 2 member A1/A2 (UGT2A1/UGT2A2) and COVID-19-related anosmia and ageusia." (PMID 38846354, 2024).
UGT2A2 also shares sentences with these, for which no sentence is quoted: Ageusia (1 paper); prostate carcinoma (1).